SALL4 (spalt like transcription factor 4)
Diseases named in the same sentence as SALL4 in open-access papers (continued):
Sharing a sentence is not in itself a finding about the gene and the disease.
dysgerminoma (10 papers, 2012 to 2025). A malignant germ cell tumor characterized by the presence of a monotonous primitive germ cell population. "Our results show that SALL4 was significantly expressed in adenocarcinoma, dysgerminoma (DSG), mixed germ cell tumors (GCTs), and immature teratoma, while OCT3/4 was highly expressed in DSG and mixed GCTs." (PMID 38928458, 2024). "In OGCTs, such as dysgerminoma, mixed germ cell tumors and immature teratoma, SALL4 is strongly expressed and often co-occurs with markers such as OCT3/4, and its presence correlates with a higher degree of malignancy and advancement and shorter progression-free survival." (PMID 41373846, 2025). "Finally, SALL4 is also expressed in the nuclei of dysgerminoma cells and confirms the germ cell origin of the neoplasm." (PMID 41373846, 2025). "The definitive diagnosis of GCNIS/GB, dysgerminoma, or other gonadal neoplasms was confirmed with histopathological features and immunohistochemical stains of markers like PLAP, SALL4, OCT3/4, TSPY, and FOXL2." (PMID 35935368, 2022). "An additional immunohistochemical examination is a valuable tool for making a reliable diagnosis, whereby a combination of positive nuclear expression of SALL4 and OCT4 and positive membranous/cytoplasmic expression of CD117 and D2-40 in a tumour is specific for a dysgerminoma in humans." (PMID 39633402, 2024). "Tumor cells were positive for OCT3/4, SALL4, and CD117 and negative for CD30 and Glypican 3, leading to a dysgerminoma diagnosis (data not shown)." (PMID 37575996, 2023).
Holt-Oram syndrome (10 papers, 2013 to 2025). Holt-Oram syndrome (HOS) is the most common form of heart-hand syndrome and is characterized by skeletal abnormalities of the upper limbs and mild-to-severe congenital cardiac defects. "Human mutations in the SALL4 gene associate with developmental complications in patients with Okihiro/Duane-Radial-ray syndrome and Holt–Oram syndrome that share key features with thalidomide embryopathy." (PMID 40524167, 2025). "In a patient with Holt-Oram syndrome and thumb agenesis, the phenotype was attributed to a variant in SALL4." (PMID 39850168, 2024). "This gene has been found to be expressed in WT and developing fetal kidney while SALL4 deletions are a common cause of Okihiro, acro-renal-ocular, and SALL4-related Holt-Oram syndromes, all of which associated with renal morphological malformations rather than WT." (PMID 26317783, 2015). "SALL4-related disorders show autosomal dominant inheritance pattern, so that haploinsufficiency of SALL4 gene leads to Duane-radial ray (DRR), IVIC, Acro-renal ocular (ARO), and rarely, Holt-oram syndromes with approximately 40–50% of cases being caused by a de novo mutations." (PMID 36829172, 2023).
melanoma (10 papers, 2015 to 2025). A malignant, usually aggressive tumor composed of atypical, neoplastic melanocytes. "Transcriptional profiling and in vitro assays using human melanoma cells demonstrate that SALL4 loss induces a phenotype switch and the acquisition of an invasive phenotype." (PMID 34417458, 2021). "Here the authors show that the embryonic stem cell factor Sall4 is a negative regulator of melanoma phenotype switching where its loss leads to the acquisition of an invasive phenotype, due to derepression of invasiveness genes." (PMID 34417458, 2021). "Surprisingly, while Sall4 loss prevents tumor formation, it promotes micrometastases to distant organs in this melanoma-prone mouse model." (PMID 34417458, 2021). "Therefore, we assessed whether loss of Sall4 affects melanoma metastasis formation in our melanoma-susceptible mouse model." (PMID 34417458, 2021). "Recently, it has been reported that knockdown of SALL4 in human melanoma cells decreases cell proliferation and impairs the expression of genes related to cell cycle, inflammation, and developmental processes." (PMID 38062245, 2024). "We find that Sall4 is the strongest upregulated transcription factor in hyperplastic, melanoma-prone murine melanocytes when compared to normal wild-type melanocytes and that Sall4 is crucial for primary melanoma growth." (PMID 34417458, 2021). "Here we show that the embryonic stem cell (ESC) factor Sall4 is re-expressed in the Tyr::NrasQ61K; Cdkn2a−/− melanoma model and that its expression is necessary for primary melanoma formation." (PMID 34417458, 2021). "In line with these in vivo results, knockdown of SALL4 in human melanoma cells leads to reduced tumor cell proliferation and to the upregulation of a set of well-known melanoma invasiveness genes, inducing an invasive cell phenotype." (PMID 34417458, 2021). "Together, our data suggest that the reduced expression of SALL4 induces human melanoma cell invasion via upregulation of known melanoma invasiveness genes, which could explain the increased metastasis burden seen upon Sall4 loss in the Tyr::NrasQ61K; Cdkn2a−/− melanoma mouse model." (PMID 34417458, 2021). "Here, we show that Sall4 is upregulated in hyperplastic murine melanoma-prone melanocytes and that its expression is essential for melanoma primary tumor growth." (PMID 34417458, 2021). "To validate the findings from our mouse model in human melanoma cells, we carried out siRNA-mediated SALL4 knockdown experiments in various human melanoma cell lines with different mutational backgrounds." (PMID 34417458, 2021). "Intriguingly, SALL4 appears to regulate a melanoma-specific invasion program through HDAC2-mediated epigenetic silencing of invasiveness genes." (PMID 34417458, 2021). "Similar to SOX10 and YY1, SALL4 is upregulated in melanoma cells and is essential for primary tumor formation and proliferation." (PMID 34417458, 2021). "The human melanoma cell lines tested displayed decreased proliferation capacities after SALL4 knockdown." (PMID 34417458, 2021). "Since our transgenic mouse model had indicated a role of Sall4 in tumor growth as well as in micrometastasis formation, we next analyzed melanoma cell migration and invasion in regards to SALL4 expression." (PMID 34417458, 2021). "Thus, SALL4 was identified as a regulator of melanoma phenotype switching from tumor formation (SALL4 overexpression) to invasiveness (SALL4 loss)." (PMID 35216168, 2022). "Importantly, however, SALL4 depletion in melanoma leads to increased invasiveness and micrometastasis formation." (PMID 34417458, 2021). "However, in contrast to previous studies on other cancer types, our results reveal that depletion of Sall4 in a murine melanoma model leads to increased micrometastasis formation while preventing sustained tumor growth." (PMID 34417458, 2021). "We therefore hypothesized that in melanoma SALL4 might exert its regulatory function in an alternative manner and have a different array of target genes." (PMID 34417458, 2021).
melanoma (continued). "This supports the hypothesis that SALL4 inhibits invasiveness-related genes in melanoma via interaction with HDACs." (PMID 34417458, 2021). "Here we identify the stem cell factor SALL4 as a regulator of melanoma phenotype switching." (PMID 34417458, 2021). "Interestingly, when we compared the numbers of primary melanomas in adult Sall4 control and Sall4−/− cko mice, we found that upon Sall4 ablation, primary tumor formation was impaired." (PMID 34417458, 2021). "Thus, SALL4 appears to regulate phenotype switching in melanoma through an HDAC2-mediated mechanism." (PMID 34417458, 2021). "To test whether knocking down SALL4 would also lead to decreased tumor growth of human xenografts in vivo, we next injected human melanoma cells 24 h after siRNA transfection subcutaneously into nude mice and analyzed tumor growth within 6 days after grafting." (PMID 34417458, 2021). "Hence, our findings identify SALL4 as a negative regulator of melanoma cell phenotype switching, i.e. the reversible change from a high proliferative/low invasive to a low proliferative/high invasive cell state." (PMID 34417458, 2021). "Here we show that SALL4 can build a protein complex together with HDAC2 also in human melanoma cells and that SALL4 and HDAC2 together directly bind to genes involved in melanocyte and melanoma biology, such as VEGFR-1, CDH2 (N-cadherin), FN1, TGFBR2, MITF, and others." (PMID 34417458, 2021). "However, in the present study, we show that while upregulation of Sall4 is crucial to sustain melanoma tumor growth, its depletion or downregulation increases invasiveness and metastasis formation in melanoma." (PMID 34417458, 2021). "By doing so, we obtained a mouse model that spontaneously developed melanoma, in which Sall4 could be deleted in melanocytes upon tamoxifen (TM) injections and Cre activity could be traced by GFP expression." (PMID 34417458, 2021). "First, to address whether cell intrinsic migratory capacities correlate with SALL4 levels, human melanoma cells were subjected to a Corning Transwell® migration assay." (PMID 34417458, 2021). "Given the re-expression of Sall4 in hyperplastic melanocytic lesions, we next addressed whether Sall4 is essential for melanoma formation." (PMID 34417458, 2021). "Moreover, murine primary melanoma displayed prominent Sall4 expression." (PMID 34417458, 2021). "Similar to SALL4, YY1 is another transcription factor (TF) that promotes melanoma initiation and tumor growth while being averse to cancer invasiveness; indeed, mice conditionally depleted for Yy1 show an increase in metastasis formation." (PMID 36551603, 2022). "Recently, the role of spalt-like transcription factor 4 (SALL4), an epigenetic player that maintains melanocyte differentiation, has been explored in a Tyr::NrasQ61K; Cdkn2a−/− melanoma mouse model." (PMID 36551603, 2022). "For example, SALL4/MLL/HOXA9 pathway is a crucial regulator of leukemic cell survival and SALL4 plays a critical role in promoting melanoma invasion by interacting with HDAC2." (PMID 35216168, 2022). "The cordycepin treatment downregulated the expression of ZEB1, HMGA2 and TWIST1 by more than 50% but had minimal effects on ADAM9, RAC1, SALL4, CTNNB1, ZEB2 and YES1 in these two melanoma cell lines." (PMID 25868853, 2015). "This further strengthens the hypothesis that SALL4 and HDAC2 together regulate melanocyte and melanoma-specific cellular processes." (PMID 34417458, 2021). "The differential gene expression obtained upon SALL4 knockdown pointed towards an upregulation of EMT-related genes and a downregulation of differentiation genes, overall suggesting acquisition of a transcriptional signature typical of melanoma cell phenotype switching." (PMID 34417458, 2021).
melanoma (continued). "The tumor cells were positive for CD68, S100, CD4 and lymphocyte common antigen, while epithelial membrane antigen, HMB-45, CK AE1/AE3, myogenin, desmin, CD1a, CD21 and SALL-4 were negative thus ruling out rhabdomyosarcoma, extrarenal rhabdoid tumor, Langerhans cell sarcoma and malignant melanoma." (PMID 31890359, 2019). "In addition, other previously identified direct targets of SALL443 have not come up in our analyses either, which suggests that SALL4 might regulate a set of specific targets in melanoma cells." (PMID 34417458, 2021).
teratoma (10 papers, 2012 to 2025). A non-seminomatous germ cell tumor characterized by the presence of various tissues which correspond to the different germinal layers (endoderm, mesoderm, and ectoderm). "In a large ovarian germ cell tumor (OGCT) series basic research study, SALL4 was positive in 11 of 15 immature teratomas, indicating a sensitivity of about 73% for this subtype." (PMID 41373846, 2025). "SALL4 shows high sensitivity in detecting immature teratoma components, with strong nuclear staining in most cases." (PMID 41373846, 2025). "Subsequent experiments involving teratoma formation and chimeric mouse generation with germline transmission capability further validated the pluripotent nature of SALL4-iPSCs." (PMID 39737935, 2024). "In a large series of 3215 tumors, SALL4 was consistently expressed in all GCTs except some trophoblastic tumors and mature components of teratomas." (PMID 39001344, 2024). "SALL4 immunostaining was 100% in testicular seminoma, EC and YSTs, 84% in choriocarcinoma, and 60% in mature teratoma." (PMID 39001344, 2024). "In order to establish an unequivocal diagnosis of immature teratoma, 3 antibodies (SALL4, GFAP, Ki-67) were employed to distinguish primitive neuroepithelial tissues from mature counterparts." (PMID 36309682, 2022). "Based on the immune-morphological similarities, expression of some SALL4 and the fact that immunereactivity for germ cell markers is often lost in a teratoma with somatic type malignancy, the peritoneal metastasis could very well be related to the previous teratomatous TGCT." (PMID 32711552, 2020). "The researchers tested approaches for the identification of pluripotency and malignancy of PSC, and they used the combination of OCT4 (EC vs. YSE and teratoma), SALL4 (positive for YSE and EC), and ZBTB16 (YSE vs. EC and teratoma)." (PMID 40650246, 2025). "In this patient’s case, the tissue mass had primitive neural tubes and daisy-like structures and was positive for the immunophenotypes SALL4, CD56, and CD99, confirming the diagnosis of immature teratoma." (PMID 36805679, 2023). "SALL4 is generally negative in mature teratomas, except for focal staining in primitive neuroepithelial or glandular areas; therefore, SALL4 is not a sensitive marker for mature teratomas, but can highlight immature foci if present." (PMID 41373846, 2025). "The expression rate of SALL4 in immature teratomas is about 75%, whereas it is not expressed in mature teratomas." (PMID 37138865, 2023). "However, SALL4 also stains EC and seminoma-like cells, and can stain focally in immature parts of teratoma, as well as sparsely in enteric-type glands, making it not specific." (PMID 40650246, 2025).
choriocarcinoma (9 papers, 2015 to 2025). An aggressive malignant tumor arising from trophoblastic cells. "In this study, SALL4 result is associated with progression-free survival of choriocarcinoma patients and CSLC’s stemness characteristics." (PMID 34732693, 2021). "Choriocarcinoma with high risk showed a higher SALL4 expression than with low risk." (PMID 34732693, 2021). "Importantly, we demonstrated that the choriocarcinoma-associated transcription factor Sall4 was increased in situ in the postmolar choriocarcinoma cohort compared to that of the complete mole counterpart." (PMID 34680590, 2021). "However, we identified that high SALL4 level was associated with poor choriocarcinoma prognosis." (PMID 34732693, 2021). "For IHC diagnosis of choriocarcinoma, the conventional method is staining for both SALL4 and human chorionic gonadotropin (HCG)." (PMID 37138865, 2023). "Overall, our study strongly supports the role of SALL4 and miR-497-5p in choriocarcinoma stemness progression and illustrates the existence of a feedback loop DNMTs/miR-497-5p/SALL4 in choriocarcinoma CSLCs." (PMID 34732693, 2021). "In the present work, we identified miR-497-5p and its target gene SALL4 as crucial factors in regulating stemness characteristics and malignant phenotype of choriocarcinoma." (PMID 34732693, 2021). "Recent studies show that gestational trophoblastic neoplasia, especially choriocarcinoma, displays high-SALL4-expression level, which can be explained by its important functions in embryonic stem cell maintenance." (PMID 34732693, 2021). "Aberrant SALL4 expression results in cell proliferation promotion in choriocarcinoma, and SALL4 is a useful biomarker to distinguish it from other trophoblastic tumors." (PMID 34732693, 2021). "Consistently, in this study SALL4 expression was analyzed in 36 cases, being upregulated in 26 choriocarcinoma tissues and gradually increasing in the choriocarcinoma with high-risk or unremission after chemotherapy." (PMID 34732693, 2021). "In this study, we demonstrated the role of SALL4 in the progression of choriocarcinoma CSLCs, being directly regulated by miR-497-5p, playing pivotal roles in stemness and malignant phenotype." (PMID 34732693, 2021). "In addition, increased expression of SALL4 and miR‐497‐5p reduction facilitates the progression of choriocarcinoma within an in vivo." (PMID 40387409, 2025). "Thus, the miR‐497‐5p/SALL4/DNMT1/3B axis emerged as a critical factor in fostering the stemness phenotype of choriocarcinoma." (PMID 40387409, 2025). "Furthermore, we divided the choriocarcinoma samples into two groups based on the mean value (6.80) of SALL4 expression." (PMID 34732693, 2021). "SALL4 appeared to be a key factor in promoting stemness phenotype of choriocarcinoma." (PMID 34732693, 2021). "Regardless, our identification of the remarkable role of SALL4 might suggest an exciting new approach for pharmacological intervention against choriocarcinoma." (PMID 34732693, 2021). "SALL4 expression is the independent risk factor correlated with the PFS of choriocarcinoma (HR = 7.045, P = 0.016).To evaluate the role of SALL4 in choriocarcinoma, SALL4 protein expression was analyzed in normal, untreated, and refractory groups by immunohistochemistry (IHC)." (PMID 34732693, 2021). "Because of DNMTs’ effect on regulating miR-497-5p, we wondered whether SALL4 regulates DNMTs in choriocarcinoma CSLCs." (PMID 34732693, 2021). "Taken together, these results strengthen the hypothesis that SALL4 overexpression and miR-497-5p silencing promoted choriocarcinoma progression also in vivo." (PMID 34732693, 2021). "The observation of a strong increase in SALL4-positive cells as the complete hydatidiform mole progresses into cancer further supports our genetic analysis, and the assumption that this signaling cascade is involved in the development of choriocarcinoma from CHM." (PMID 34680590, 2021).
choriocarcinoma (continued). "We found the strong expression of SALL4, an upstream regulator of TGF-β, in postmolar choriocarcinoma, compared to moles, in which its expression was almost null." (PMID 34680590, 2021). "Due to the difficulty in obtaining choriocarcinoma clinical specimens with strictly according to FIGO staging, we cannot evaluate the correlation between tumor staging and SALL4 exactly." (PMID 34732693, 2021). "The portion including large carcinoma cells exhibited positive-hCG, p40, PLAP, SALL4, EMA and CD146, which matched with a typical pattern of the syncytiotrophoblast-like component in choriocarcinomas." (PMID 32990826, 2020). "As our data showed, two choriocarcinoma complicated with ETT were negative in the expression of SALL4." (PMID 33219408, 2021). "Silencing miR-497-5p and SALL4 promotes choriocarcinoma progression and forms a feedback loop with DNMT-mediated epigenetic regulation, playing a crucial role in stemness maintenance in choriocarcinoma." (PMID 34732693, 2021). "Two choriocarcinoma complicated with ETT were negative in the expression of SALL4." (PMID 33219408, 2021).